TNF (tumor necrosis factor)
Diseases named in the same sentence as TNF in open-access papers (continued):
Sharing a sentence is not in itself a finding about the gene and the disease.
infection (continued). "Quantitative real-time PCR assay showed that the TNF-α mRNA expression in the HKO infected macrophage was unaltered compared with CT, OE, and CM infected cells up to 72 h infection period." (PMID 34534548, 2021). "Infection with either of the four strains resulted in an up-regulation of IL-6, IL-10, IFN-λ, IFN-γ, IP-10, MX-2, and TNF-α expression in the range of 10- to 1000-fold compared to non-infected hamsters." (PMID 34049240, 2021). "The levels of cytokines (IL-6, TNF-α, IL-1β) and chemokine (CCL2) were upregulated in response to the B.1.1.7 and B.1.351 infection in the lungs." (PMID 35062231, 2021). "Moreover, it has been shown that the intraperitoneal administration of proinflammatory cytokines (IL-1, TNF-α, and IL-6), alone or combined, temporally induces anhedonia and that infection with bacteria of the genus Mycobacterium may also produce memory deficits and anhedonia." (PMID 34576830, 2021). "Pro-inflammatory cytokines IL-2, TNF-α, IL-17α, IFN-γ, IL-1β, and MIP-3α are significantly elevated in infection-naïve CF mice (p < 0.050)." (PMID 34475490, 2021). "As with the gamma response, the Mtb-specific CD4+TNF- α+T cells and CD8+ TNF-α+T cells elicited by Mtb CW stimulation at 3 weeks post-infection was significantly higher in the high dose group compared to the low dose group." (PMID 34484203, 2021). "Our results revealed that DATS significantly reduced the expression of IL-6 and TNF-α in H9N2 AIV-infected cells and enhanced the expression of RIG-I and IFN-β in the lungs to defend H9N2 AIV infection in mice." (PMID 34412671, 2021). "The TNF-α mRNA expression in the trachea and lung of group IV was lower compared with expression levels in groups I, II, and III from day 1 to 7 post-infection." (PMID 34988139, 2021). "In contrast, mice treated with D. pigrum 040417 had significantly reduced levels of BAL TNF-α and CCL2 compared with controls after 32 hours post-infection." (PMID 34207076, 2021). "Typically, IL-17, AGE-RAGE, TNF, HIF-1, PI3K-AKT, NOD-like receptor, T/B cell receptor, and virus (EBV and hepatitis virus) infection-related pathways were the most significant pathways involved." (PMID 34394391, 2021). "It has been suggested that infection can alter signaling pathways via indirect effects such as the host-mediated immune (INF, Interleukin, TNF) and hormonal response." (PMID 34361972, 2021). "As parasites are not present in the CNS at this stage, the changes observed in the prefrontal cortex probably result as a consequence of the systemic response to infection and possibly are dependent on cellular responses evoked by IFN-γ, TNF-α, and MCP-1." (PMID 34303703, 2021). "The pattern of TNF-a induced by BS26 in vivo was similar to those patterns of cytokines induced by P1/7, peaking at 8 h post-infection and gradually decreasing thereafter." (PMID 34357984, 2021). "When examining TIGIT+NK cells, they harbored fewer functional cells that released CD107a, TNF-α, and IFN-γ than TIGIT−NK cells in both HIV-1-positive individuals in all infection stages and in HIV-1-negative donors (all P < 0.05)." (PMID 33717085, 2021). "Further RT-PCR analyses determined that the levels of IFNB1, IFIT2, IFIT1, TNF and the proinflammatory cytokines CCL20 and IL6 were enhanced by RTN3 knockdown during VSV infection, while the amplification of VSV was compromised." (PMID 34313226, 2021). "Interleukin-2 (IL-2) and tumor necrosis factor (TNF) were lost early, whereas interferon-γ (IFN-γ) production persisted longer after infection." (PMID 34354714, 2021). "Most importantly, when comparing young infected mice to middle-aged infected mice, there was an upregulation of mRNA for HMGB-1, tumor necrosis factor (TNF), IL-1β, and C1q within 7 days post-infection in middle-aged mice." (PMID 33924771, 2021). "We also detected increased cleavage of caspase-8 and caspase-3 in vivo upon infection of OTUB1FL mice with Lm and treatment with DGal/TNF, respectively." (PMID 33712742, 2021).
infection (continued). "Here, CD300F plays a role in dampening the inflammatory response during infection, most likely via reduction of CXCL10, TNF-α, and IFN-γ production in microglial cells." (PMID 34279684, 2021). "Proinflammatory cytokines, such as IL-1β, IL-6, IFNα/β, and TNFα, produced upon TMEV infection via TLR-mediated signals, further upregulate the production of chemokines." (PMID 34067536, 2021). "Again, B. dorei-treatment significantly reduced the levels of IL-1β, IL-6, TNF-α, IL-10, MCP-1 and IP-10 in lung compared with PBS-treated infection mice at day 7 p.i., to a comparable degree relative to the oseltamivi treatment." (PMID 35154087, 2021). "At 7-weeks post-infection the human cytokines IFN-γ, TNF-α, IL-12p40, IL-10 and IL-13 were elevated in humanized mice infected with HTLV-1, S. stercoralis or with the dual infection, as compared to background controls." (PMID 34314415, 2021). "After infection diagnosis, PGE2 showed only positive correlations with pro-inflammatory cytokines such as TNFα, IL-2, IL-15." (PMID 33617528, 2021). "Inflammatory cytokines such as IFN-γ, TNF-α, and IL-21 have been shown to play a critical role in the severity of SARS-CoV-2-mediated infection." (PMID 34199203, 2021). "T CD8+ is also activated against infection and by releasing IFN-γ and TNF-α cytokines, which consequently increases the antiviral responses." (PMID 33746897, 2021). "Additional immune mediators such as TNFα, reactive nitrogen intermediates, TLR2, and the inflammasome have been identified following infection with Ft." (PMID 33946283, 2021). "The results clearly demonstrate an early differentiation in the immunity following low dose and high dose infection, largely represented by differences in the IFN-γ and TNF-α response by Mtb-specific T cells in the BAL." (PMID 34484203, 2021). "Protection against lethal infection; reduced granulocyte recruitment; reduced expression of proinflammatory cytokines CXCL10, CXCL1, CCL2, and TNF." (PMID 34557097, 2021). "As expected, the rgH3N2 and rgH3N2 4xM2e groups presented significantly lower amounts of TNF-α, IFN-γ and IL-6 than the naïve group after infection with rgH5N1." (PMID 33603072, 2021). "In 2017, we described a new role for transmembrane TNF-α (tm-TNF-α), facilitating the infection of CD4-negative podocytes and tubular epithelial cells cultured from children with HIV-associated kidney diseases." (PMID 33044676, 2021). "To access the therapeutic roles of anti-cytokine mAb in vivo, we inoculated 5-day-old neonatal mice via i.m. with 104 TCID50 CVA2 and administered with isotype control, anti-TNF-α, anti-IL-6, and anti-MCP-1 mAbs via the i.p. route at 12 h post infection." (PMID 34122374, 2021). "We found that infection of primary macrophages with influenza PR8 or CA09 led to a robust increase in both IL-6 and TNFα." (PMID 34899695, 2021). "A majority of studies conclude that antibodies, driven by a TH2-like response, have a functional role in protection from infection, while TH1/TH17 cytokines such as IFN-γ, TNF-α, IL-17, and IL-6, have also been correlated with protection or bacterial killing." (PMID 34835150, 2021). "More broadly, our results suggest that expanding beyond TNF and type I IFNs as markers of TLR activation may offer both new insights into mechanisms and consequences of TLR signaling and into the links between TLR activation and control of pathogenic infection." (PMID 34755600, 2021). "P. vivax infection reduces the total number of CD8+ T cells, especially memory cells, during the blood-stage of infection but enhances the number of memory CD8+ T cells expressing IL-10, TNF-α, and IFN-γ." (PMID 33804076, 2021). "Additionally, our pathway analysis revealed seven genes, IL-4, IFNγ, TLR4, CXCL8, IL-18, CSF2 and TNFα, are involved in the morphological and behavioral changes of macrophages, monocytes, granulocytes, and dendritic cells (DCs) and their recruitment into infection sites." (PMID 34753991, 2021).
infection (continued). "The BCG-CWS-adjuvanted (S+BCG-CWS) vaccination effectively attenuated the production of inflammatory cytokines including IL-6, TNF-α, and IFN-γ, in the lungs from all aged mouse groups (6 D, 2 W, 6 W, and 20 M) after lethal infection." (PMID 34063125, 2021). "A cytokine panel array of the serum of mice with 60 days of infection demonstrated that S. mansoni increased the circulating levels of IFN-γ, TNF-α, IL-12, and MCP-1." (PMID 34303703, 2021). "The concentrations of IL-4, IL-5, TNF, and IFNγ in the BALF of BALB/c pups were also higher, though not statistically different, than in C57BL/6 pups at day 27 post-infection (Figure A2E–G)." (PMID 34682248, 2021). "We observed that in vitro infection with GCRV induced the expression of IFN1, Mx2, IL-1β, and TNFα, indicating the initiation of antiviral response." (PMID 34068469, 2021). "In the lymphocytic choriomeningitis virus (LCMV) infection model, combination of cytokines including TGF-β, IL-33 and tumor necrosis factor (TNF) enhances the establishment of CD8 TRM cells via the downregulation of S1pr1." (PMID 34572004, 2021). "TNF-α, IL-Iβ, IL-6 and IFN-γ, belonging to the pro-inflammatory cytokines, are involved in promoting acute inflammation to defense against infection." (PMID 34275451, 2021). "Four days after infection, liver organoid cultures from five different donors were treated with LCL-161, recombinant TNF or the combination of both, and HBV DNA levels in culture supernatants were quantified after 4 days of treatment using qRT-PCR." (PMID 34162831, 2021). "Total bone marrow and spleen cells from 24 h post-secondary infection were cultured and stimulated with PMA and ionomycin for 6 h to assess cytokine production (TNF-α and IL-6) by LKS+ and LKS– cells by intracellular flow cytometry." (PMID 34975887, 2021). "IL‐1β, IL‐6, and TNF‐α are important for acute phase protein production and fever induction, while IL‐12, IL‐18, and IFN‐γ recruit neutrophils to the site of infection and elicit a T helper type 1 (Th1) adaptive immune response." (PMID 33970545, 2021). "In malaria, excessive production of inflammatory cytokines, including TNF-α, IL-6, IL-12, and IFN-γ, at the early stages of infection is a key contributor to pathogenesis." (PMID 33330947, 2021). "Burned mice infected with P. aeruginosa M2 showed increased circulating proinflammatory cytokines (IL-6, IL-1β, TNF-α, and IFN-γ) and a rise in anti-inflammatory IL-10 late during infection once clinical symptoms were observed." (PMID 34152806, 2021). "In HBV infected chimpanzees, CD4 and CD8 T cells helped in resolution of infection by producing interferon-γ (IFN-γ) and tumor necrosis factor- α (TNF-α) cytokines." (PMID 34071064, 2021). "The level of TNF-α increased at 24 and 48 h, accompanied by the decrease of intracellular CFU, while the level of TNF-α was similar to that of the infection group at any time." (PMID 35003120, 2021). "For instance, colonization by P. gingivalis stimulates host cells to release various proinflammatory cytokines, such as interleukin-1β (IL-1β) and tumor necrosis factor-α (TNF-α), and recruits neutrophils to the site of infection." (PMID 33860060, 2021). "Despite some variation between individual mice, BALF samples from LVS- and fpt mutant-infected mice showed significantly elevated levels of IFN-γ, TNF-α, IL-1β, IL-12p70, IL-10, IL-2, and KC/GRO compared to mock infection." (PMID 34202420, 2021). "T-helper cell (Th1)-type cytokines, such as TNF-α, IL-6 and IL-1β, and Th2-type cytokines, such as IL-10 and IL-4, were differentially expressed in M. fortis and BALB/c mice in the early stage of infection." (PMID 34689797, 2021). "Fth1−/− mice had lower levels of circulating tumor necrosis factor (TNF)-alpha, interferon-gamma (IFN-gamma) and interleukin (IL)-6 than Fth1+/+ mice, 60 days after infection." (PMID 35008695, 2021).
infection (continued). "And in fact, brain tissue of chronically infected TKO mice showed increased TNF and IFNγ as well as increased production of these cytokines released by CD4+ T cells in the chronic phase of infection." (PMID 33968021, 2021). "In spite of equal microbicidal activity, it was observed that decitabine modulated the release of inflammatory cytokines, such as IL-1β, TNF-α, and IFN-γ, which showed a significant reduction after 7 days of infection when compared to the DMSO group." (PMID 33921194, 2021). "As observed for day 1 post infection, in the SIM group we observed increased percentage of multifunctional effector CD4 T cells expressing IFNγ/TNFα or IL-17/TNFα." (PMID 34925371, 2021). "As evident from in vitro study by one of the authors, induction of inflammatory cytokines/chemokines including IL-6, IL-8, TNF-α, and RANTES was observed within 12 h of infection in genotype 1 HEV infected lung epithelial cells." (PMID 34502167, 2021). "L-Kyn reduced the number of TNF-α+ and IL-1β+ CD11c+ cells at both infection periods but increased the number of IL-12 and TGF-β expressing CD11c+ cells by 96 hours of infection." (PMID 33936043, 2021). "In control animals, we noted a significant increase in proinflammatory cytokines (IL-1α, IL-1β, IL-6, and TNF-α), and chemokines (RANTES/CCL5 and CXCL1) coupled with the surge of G-CSF in response to infection." (PMID 33514747, 2021). "Consistent with this idea, BMDMs and MEFs from Rnf122−/− mice produced increased levels of IFNα and IFNβ, TNFα and IL6 in response to infection with VSV and SeV." (PMID 33808506, 2021). "Neutralization of IL-2 increased the numbers of recently activated CD4+CD69+ T cells and memory CD4 and CD8 T cells after three weeks of infection and the numbers of splenic T cells producing IFN-γ, TNF-α and IL-10." (PMID 34869064, 2021). "Whereas LPS stimulation induced 8 of 12 cytokines tested by 24 h post‐infection (p.i.), cytokine induction by DENV was limited to TNF‐α, IFN‐γ and IP‐10 at 24 h suggesting a specific role of these cytokines in initiating the macrophage response to DENV." (PMID 34287854, 2021). "IDO is induced by infection and inflammation through pro-inflammatory cytokines and mediators, mainly by IFN-y, but also IFN-α, TNF-α and LPS." (PMID 35046929, 2021). "Suggesting low systemic response, the blood of mice trained 9 weeks contained lower levels of a broad range of cytokines (IL-1β, IL-6, IL-10, IL-12p40, IL-17A, IL-18, IFNγ, TNF, CCL2 and CXCL5) 2 days after infection with L. monocytogenes." (PMID 34603295, 2021). "infections result in the induction of CD4+ T cells that are either IFN-γ-single, or (IFN-γ/TNF-α)-double cytokine-producing T-helper 1 cells." (PMID 34204170, 2021). "We demonstrate that the production of proinflammatory cytokines, especially TNF-α, during GPS4 infection was involved in barrier dysfunction." (PMID 34674760, 2021). "At 6, 24, 48, and 72 h post infection, blood samples were collected, and the serum levels of 10 cytokines (GM-CSF, IL-1β, IL-6, IL-10, TGF-β1, IFNγ, IL-4, IL-8, IL-12p40, and TNF-α) were assessed." (PMID 33665221, 2021). "In molluscs, homologues of the vertebrate TNF-α and TNFR have been described and respond to infection." (PMID 34659116, 2021). "Four weeks after infection, the mRNA expression of IFN-γ, TNF-α, and TCF-7 in the lungs of mice was measured." (PMID 33628846, 2021). "Moreover, TNFα activation of the NFκB pathway might potentially enhance infection progression." (PMID 34415956, 2021). "The data demonstrated that at day 1 post infection, the SIM group showed activated multifunctional vaccine-specific CD4 T cells (IL-17+/TNFα+ Th17 or IFNγ+/TNFα+ Th1 T cells) in the GT." (PMID 34925371, 2021). "However, when microglia are activated by injury and infection, they produce various pro-inflammatory mediators (free radicals), including nitric oxide (NO), reactive oxygen species (ROS), and cytokines, such as interleukin (IL)-1β, IL-6, and tumor necrosis factor (TNF)-α." (PMID 34234892, 2021).
infection (continued). "Consistent with our results, in vivo infection of lungs with A. fumigates in IPA mice enhanced inflammatory-cytokine-mediated pathology by increasing the production of IL-17, IL-1, and TNF by eosinophils and macrophages." (PMID 35010001, 2021). "Here, we show that at the beginning of the infection, the BALB/c mice increased the proportion of peritoneal M1 MΦ responsible for the increased levels of TNFα detected at this time." (PMID 34832600, 2021). "The cytokines are complemented by infection and inflammation related proteins such as IL6 or IL18 and TNF, the key players in infectious disease states with both beneficial and harmful, pleiotropic activities." (PMID 35145507, 2021). "At 24 h post-infection, the percentages of infection at an MOI of 5 were 1.79%, 57.40%, 1.98%, and 60.08% for the mock-infected, DENV2-infected, TNF-α, and TNF-α plus DENV2 treated cells, respectively." (PMID 34696472, 2021). "In conclusion, infection of hamsters with G. lamblia lowered NO production, while increasing IL-6, IFN-γ, and TNF-α." (PMID 33919165, 2021). "Tumor necrosis factor alpha (TNF-α), IL-2, and granulocyte colony-stimulating factor (G-CSF) increased markedly following infection and remained relatively high throughout, with the exception of G-CSF, which dropped dramatically on 25 DPI." (PMID 33436428, 2021). "TNF-α, IFN-γ and IL-12 secretion were significantly lower in miR-378b−/− mice than wild-type mice at different time points after infection, except for TNF-α four weeks post infection." (PMID 34067003, 2021). "The lung homogenates from Nlrp3−/− mice showed significantly higher levels of IL-1β, IL-6, IL-10, IL-12p70, G-CSF, GM-CSF, TNF-α, and RANTES than the wild-type mice on day 3 post-infection." (PMID 34690967, 2021). "The T helper 1 cells release cytokines (interferon gamma [IFN-γ] and tumor necrosis factor alpha [TNF-α]) at the site of infection and activate macrophages and DCs to produce cytokines and antimicrobial peptides for containment of the infection." (PMID 33087432, 2021). "Upon infection, IRF1 is first activated by PRR signaling and then sustained via autocrine/paracrine TNF-α and IL-6." (PMID 34607464, 2021). "Our data showed that at day 50 of infection with S. mansoni increased circulating IFN-γ, IL-6 and TNF levels were observed in mice with adequate nutritional status." (PMID 33815321, 2021). "After the TNF-α treatment, these iCMs were subjected to SARS-CoV2 pseudoviral infection for 24 h, followed by harvesting of iCMs and immunofluorescence staining (upper)." (PMID 34576032, 2021). "The MFI of TNF-α released by TIGIT+NK and TIGIT−NK cells in the first, third and twelfth month of infection was lower than that in HIV-1-negative donors." (PMID 33717085, 2021). "It has also been shown to alter the expression of some host factors, including enzymes/mediators and co-receptors such as ACE2, as well as ILs, TNF-α, IFN-γ, Nrf2, Bax/caspases, and Beclin/LC3 to facilitate cellular infection and subsequent complications." (PMID 34068970, 2021). "To determine the role of TNC in the development of systemic inflammation, we measured the plasma levels of TNF-α, IL-6, and CCL2 as markers of systemic inflammation 24 and 42 h after the beginning of infection." (PMID 33776992, 2021). "Classically-activated M1 monocytes respond to proinflammatory cytokines such as tumor necrosis factor (TNF)-α and interferon (IFN)-γ by becoming macrophages, which propagate the inflammatory response toward infection." (PMID 34338633, 2021). "The infection of Hoxb8 neutrophils with A. phagocytophilum has been shown previously to induce the secretion of MIP-1α, RANTES and TNF." (PMID 33747981, 2021). "EV-A71 infected cells produce cytokines such as TNF-α, IFN-γ, and IL-6, which play an important role in controlling viral replication and infection at the early stage." (PMID 34493781, 2021).